PDX1 (pancreatic and duodenal homeobox 1)
Description:
Activates insulin, somatostatin, glucokinase, islet amyloid polypeptide and glucose transporter type 2 gene transcription. Particularly involved in glucose-dependent regulation of insulin gene transcription. As part of a PDX1:PBX1b:MEIS2b complex in pancreatic acinar cells is involved in the transcriptional activation of the ELA1 enhancer; the complex binds to the enhancer B element and cooperates with the transcription factor 1 complex (PTF1) bound to the enhancer A element. Binds preferentially the DNA motif 5'-[CT]TAAT[TG]-3'. During development, specifies the early pancreatic epithelium, permitting its proliferation, branching and subsequent differentiation. At adult stage, required for maintaining the hormone-producing phenotype of the beta-cell.
Synonyms: PDX-1; GSF; IUF-1; IDX-1; STF-1; IPF1; MODY4; IUF1; PAGEN1
Tractability: No criterion of Open Targets' tractability assessment is met for any kind of drug.
Gene: Protein-coding gene on chromosome 13 (27,920,000 to 27,926,313, forward strand). Ensembl gene ENSG00000139515.
Subcellular location: Nucleus; Cytoplasm, cytosol
Subcellular location (Human Protein Atlas): Nucleoplasm
Pathways (Reactome):
Developmental Biology: Developmental Lineage of Multipotent Pancreatic Progenitor Cells; Developmental Lineage of Pancreatic Acinar Cells; Developmental Lineage of Pancreatic Ductal Cells; Regulation of gene expression in beta cells; Regulation of gene expression in early pancreatic precursor cells
Gene Ontology:
Molecular function: DNA-binding transcription factor activity; sequence-specific double-stranded DNA binding; DNA-binding transcription activator activity, RNA polymerase II-specific; DNA-binding transcription factor activity, RNA polymerase II-specific; RNA polymerase II cis-regulatory region sequence-specific DNA binding; RNA polymerase II-specific DNA-binding transcription factor binding; chromatin binding; DNA binding; promoter-specific chromatin binding; protein-containing complex binding; sequence-specific DNA binding
Biological process: insulin secretion; positive regulation of transcription by RNA polymerase II; type B pancreatic cell differentiation; animal organ morphogenesis; generation of precursor metabolites and energy; glucose mediated signaling pathway; positive regulation of insulin secretion; regulation of transcription by RNA polymerase II; transcription by RNA polymerase II; animal organ regeneration; cell differentiation; cellular response to acadesine; DNA-templated transcription; endocrine pancreas development; epithelium development; negative regulation of DNA-templated transcription; pancreas development; positive regulation of cell population proliferation; positive regulation of DNA-templated transcription; regulation of DNA-templated transcription; regulation of gene expression; response to alkaloid; response to chlorate; response to cytokine; response to fatty acid; and 12 more
Cellular component: nucleoplasm; chromatin; nucleus; cytosol; nuclear speck
Genetic constraint (gnomAD): Loss-of-function variants: 7 observed, 7.73 expected, observed/expected ratio (o/e) 0.91, 90% interval 0.51 to 1.64. That is too few expected variants to judge how well the gene tolerates losing a copy. Missense variants: 449 observed, 387.09 expected, observed/expected ratio (o/e) 1.16, 90% interval 1.07 to 1.25. Synonymous variants: 232 observed, 181.79 expected, observed/expected ratio (o/e) 1.28, 90% interval 1.15 to 1.42.
Gene-disease validity (ClinGen):
ClinGen rates the evidence that PDX1 causes each of these diseases.
pancreatic agenesis 1 (autosomal recessive): Definitive. Any pancreatic agenesis in which the cause of the disease is a mutation in the PDX1 gene.
monogenic diabetes (autosomal dominant): Moderate. Diabetes mellitus that is caused by mutations in a single gene.
Homologues: Orthologues: chimpanzee PDX1 (99% identical), macaque PDX1 (99% identical), pig PDX1 (94% identical), dog PDX1 (92% identical), rat Pdx1 (89% identical), mouse Pdx1 (88% identical), rabbit PDX1 (88% identical), guinea pig PDX1 (55% identical). Paralogues in human: HOXA3 (33% identical), HOXB3 (33% identical), HOXD3 (31% identical), HOXB2 (28% identical), GSX2 (27% identical), HOXA2 (26% identical), HOXB4 (24% identical), HOXB1 (23% identical), HOXB5 (23% identical), HOXA1 (23% identical), HOXA4 (23% identical), HOXD4 (23% identical), and 30 more.
Diseases named in the same sentence as PDX1 in open-access papers:
PDX1 is named in the same sentence as 172 diseases in open-access papers, as found by Europe PMC text mining. Sharing a sentence is not in itself a finding about the gene and the disease. The quoted sentences say what the papers report.
diabetes (238 papers, 2001 to 2026). "Genetic variants in PDX1 have been associated with monogenic forms of diabetes, including maturity-onset diabetes of the young type 4 (MODY4)." (PMID 41898807, 2026). "PDX1 mutations are associated with multiple forms of diabetes, including syndromic, neonatal, mature onset diabetes of the young (MODY), and type 2 diabetes." (PMID 40485586, 2025). "Much like the deletion of Pdx1, loss of Ogt in the β-cells results in progressive diabetes and reduced β-cell mass, accompanied by significant reductions in islet Pdx1 protein levels." (PMID 40134803, 2025). "Heterozygous mutations in the PDX1 gene have been reported in susceptibility to type 2 diabetes mellitus (OMIM: 125853) and MODY type IV (OMIM: 606392), both with autosomal dominant inheritance." (PMID 39859454, 2025). "β-cell-specific knockdown of Pdx1 disrupts glucose homeostasis and causes mature-onset diabetes in mice." (PMID 40134803, 2025). "Globally, PDX1 variants segregating with monogenic diabetes (PDX1-MODY) have been reported in only a few families, and due to their rarity, the clinical characteristics of affected individuals remain poorly defined." (PMID 41153735, 2025). "Maturity-onset diabetes of the young type 4 (MODY4, PDX1-MODY) is a monogenic diabetes caused by the PDX1 gene." (PMID 40379627, 2025). "The pdx1 gene is a pancreatic transcription factor that in humans is linked to genetic forms of diabetes, thus allowing the elucidation of the mechanisms behind hyperglycaemic pathologies." (PMID 38279951, 2024). "This is an interesting finding, as previous reports documented that a large fraction of diabetic patients with mutant Mapk8ip1 allele were also carriers of a Pdx1 mutation, which was previously associated with a late-onset form of diabetes." (PMID 36837926, 2023). "For example, it helped to reveal the genetic mechanism underlying transcription factor PDX1-mutation-associated impaired glucose tolerance in patients with an increased risk for diabetes." (PMID 37408278, 2023). "She carries a likely pathogenic PDX1 variant (Ala228GlyfsTer33) which is similar to PDX1/Pro63ArgfsTer60, the only PDX1 variant linked to diabetes with well demonstrated dominant-negative effect." (PMID 36178555, 2023). "Reading through the literature, MODY_4 or PDX1_MODY is a rare form of monogenic diabetes caused by heterozygous variants in PDX1 that leads to pancreatic beta-cell dysfunction." (PMID 38162681, 2023). "Using a PDX1-mutant-derived iPSC line and subsequent differentiation, the study deduced that amino acid mutations in PDX1 impair pancreatic endocrine formation and β-cell function, contributing to a predisposition for diabetes." (PMID 37408278, 2023). "This key finding emphasizes the consequential role of PDX1 gene mutations in the onset of diabetes and associated insulin resistance." (PMID 38333726, 2023). "Based on ChIP analysis, ATF5 has been proven to be the downstream target of pancreatic duodenal homeobox-1 (Pdx1), which is an important pathogenic gene in diabetes." (PMID 37095454, 2023). "Further, we should not exclude a model in which aberrant overexpression of Bridge-1/PSMD9 is involved in the PDX1 proteasomal degradation pathway or is otherwise implicated in β cell mass loss and diabetes." (PMID 36272648, 2022). "After silencing the PDX-1 gene in neonatal mouse islet β cells, insulin secretion is defective, causing impaired glucose tolerance and diabetes in adulthood." (PMID 36551213, 2022). "As a nexus of β-cell response to glucose stimulus, it is unsurprising PDX1 dysfunction, through up/downregulation or mutation(s), is linked to the onset of diabetes." (PMID 36272648, 2022). "On the other hand, mice expressing mutated PDX1 develop diabetes at weaning concomitantly with reduced beta-cell proliferation and beta-cell area." (PMID 36187092, 2022).
diabetes (continued). "Mutations in PDX1 are associated with T2D and multiple types of monogenic diabetes including Mature Onset Diabetes of the Young (MODY) and neonatal diabetes." (PMID 36272648, 2022). "MODY four is a rare monogenic subtype of diabetes mellitus, it is caused by different various mutations in PDX1 gene and its transactivation domain." (PMID 36589234, 2022). "PDX1 is also linked to diabetes pathogenesis; in type 1 diabetes (T1D) PDX1 autoantibodies have been detected, while in type 2 diabetes (T2D), PDX1 expression levels are compromised." (PMID 36589234, 2022). "It is likely that reduced expression levels of MafA and PDX-1 and/or incretin receptor in β-cells are closely associated with β-cell failure in type 2 diabetes mellitus." (PMID 35453568, 2022). "Impaired expression or certain mutations of PDX1 during embryonic development are linked to pancreatic agenesis and the onset of diabetes with age." (PMID 36272648, 2022). "Later in life, high PDX1 levels are important to maintain the identity of endocrine β-cells and heterozygous variants of PDX1 have been linked to the development of Mature Onset Diabetes of the Young (MODY)." (PMID 34926472, 2021). "We, therefore, postulate that compromised necroptosis contributes to diabetic disease pathogenesis by conferring full penetrance on the PDX1 mutation." (PMID 33795639, 2021). "Fibroblasts from patients with heterozygous point mutations in the PDX1 transactivation domain were successfully reprogrammed to iPSCs and can be used to study diabetes-associated pathomechanisms." (PMID 34079523, 2021). "In a family with multiple generations of diabetes and several early onset diabetic siblings, we found the previously reported P33T PDX1 damaging mutation." (PMID 33795639, 2021). "For example, homozygous mutations in the PDX1 gene result in early onset diabetes associated with pancreatic agenesis and maternal miscarriages." (PMID 34079523, 2021). "Data from several studies suggested that deletion and mutation in PDX1 caused overt diabetes and maturity-onset diabetes of the young." (PMID 34696776, 2021). "Homozygous mutations in the transcription factor Pdx1 cause pancreatic agenesis, but heterozygous mutations lead to manifestations of diabetes." (PMID 34366878, 2021). "Human patients with PDX1 heterozygous inactivating mutations exhibit MODY4 diabetes caused by defects in β cell function and/or the maintenance of β cell mass in adults." (PMID 34295307, 2021). "We identified associations for variants in GCK, HNF1A and PDX1, which are known to be involved in Mendelian forms of diabetes." (PMID 34732801, 2021). "Mice with a selective disruption of the Pdx1 gene in β-cells develop diabetes associated with a reduction in insulin production and GLUT2 expression." (PMID 34638652, 2021). "Pdx1+/− β-cells have an increased susceptibility to ER stress and high-fat diet imposes increased ER stress to β-cells of Pdx1+/− mice leading to overt diabetes." (PMID 31682591, 2020). "PDX1 (pancreatic and duodenal homeobox 1) is a diabetes susceptibility gene involved in pancreas development and regulates mitochondrial DNA transcription in pancreatic β-cells." (PMID 32986742, 2020). "PDX1 is a regulator of pancreas development and β cell differentiation and its antisense lncRNA, PLUT1, is potentially associated with diabetes and affects chromatic structure and the transcription of PDX1." (PMID 30898084, 2019). "In humans, mutations of PDX1 cause a monogenic form of diabetes (MODY4) as well as permanent neonatal diabetes, and complete loss of PDX1 function results in pancreas agenesis." (PMID 30590691, 2019). "Ablation of either Pdx1 or Ptf1a causes pancreatic agenesis or diabetes and wide gastro-duodenal deformations." (PMID 30425728, 2018). "Utilizing NGS based strategy, we have recently reported a wider spectrum of MODY mutations involving NEUROD1 and PDX1 in patients with young onset diabetes (<30years) in India." (PMID 28095440, 2017).
diabetes (continued). "Inactivation of the mouse Pdx1 gene results in the loss of the β-cell phenotype and maturity onset diabetes." (PMID 28763492, 2017). "Bi-DOCS were associated with genes related to pancreas development and beta-cell function, including transcription factors mutated in monogenic diabetes (PDX1, NKX2-2, HNF1A; FDR < 0.05)." (PMID 29107594, 2017). "This notion is also supported by the identification of maturity-onset diabetes of the young 4 (MODY4), one type of diabetes caused by monogenic defects (heterozygous) in the PDX1 gene." (PMID 29096722, 2017). "Pdx1+/− mice were therefore used to characterize and define a highly relevant animal model for studying the pathophysiology of the type of diabetes that is primarily caused by pancreatic defects." (PMID 27406855, 2016). "In this work, we describe a pdx1 mutant zebrafish recently generated through the Zebrafish Mutation Project27 as a new model of diabetes." (PMID 26384018, 2015). "In mice, β-cell-selective disruption of pdx-1 led to the development of diabetes with increasing age and was associated with reduced insulin and GLUT-2 (a glucose-sensing and -transporting molecule located on the surface of β-cells) expression." (PMID 25695047, 2015). "Mice homozygous for a null mutation in Pdx1 fail to develop a pancreas, whereas restricted inactivation of Pdx1 in the murine β-cell produces insulin deficiency and diabetes." (PMID 25841258, 2015). "In this work, we characterize pancreatic islet development and function in zebrafish mutant for pdx1, a gene which in humans is linked to genetic forms of diabetes and is associated with increased susceptibility to Type 2 diabetes." (PMID 26384018, 2015). "Pancreatic overexpression of dominant-negative FGFR1c using the Ipf1/Pdx1 promoter has previously been shown to decrease the number of β-cells, change islets morphology, and to cause diabetes in mice." (PMID 25427253, 2014). "Inclusion of the PDX1 gene in mutation screening for permanent neonatal diabetes is recommended as a genetic diagnosis reveals the mode of inheritance, allows accurate estimation of recurrence risks and confirms the requirement for insulin treatment." (PMID 23320570, 2013). "As expected, mutations in PDX1 were more common in cases of isolated permanent neonatal diabetes born to consanguineous parents compared with outbred cases (2/17 vs. 1/86)." (PMID 23320570, 2013). "A recent report described two cousins with a homozygous hypomorphic PDX1 mutation causing permanent neonatal diabetes with subclinical exocrine insufficiency." (PMID 23320570, 2013). "Mice with β-cell-specific ablation of pdx-1 develop overt diabetes, whereas heterozygosity for the null mutation of pdx-1 results in decreased insulin expression/secretion and predispose islets to apoptosis." (PMID 24705209, 2013). "TG mice had impaired glucose tolerance and some of them indeed developed diabetes due to the reduction of β cell mass, which is associated with decreased Pdx1 and MafA in β cells." (PMID 22384192, 2012). "In humans, mutations in one allele of the Pdx1 gene are associated with adult-onset diabetes (a form of monogenic diabetes), while homozygous mutations in Pdx1 result in pancreatic aplasia." (PMID 22611393, 2012). "Mutations in the pancreatic and duodenal homeobox 1 (PDX1/IPF1) gene are a known cause of monogenic diabetes (OMIM 600733)." (PMID 21569088, 2011). "Pancreas/duodenum homeobox protein 1 (Pdx1) and diabetes‐related genes are implicated in beta cell survival through direct regulation of ATF5, a downstream target of ATF4, modulated by eIF4E‐binding protein 1 (4ebp1) within the mammalian target of rapamycin (mTOR) pathway." (PMID 39668579, 2025). "Mutations in PDX1 are associated with insulin-dependent diabetes mellitus." (PMID 40273002, 2025). "In diabetes, reduced Pdx1 expression contributes to β-cell loss and dysfunction." (PMID 40809178, 2025).